FAM13A (family with sequence similarity 13 member A)
Synonyms: FAM13A1; KIAA0914; ARHGAP48
Tractability: PROTAC: ubiquitination databases record sites on it.
Safety:
Unwanted effects reported when the protein is acted on. In parentheses: how it was acted on, where the effect was seen, and who reports it.
body mass index (source: ClinPGx)
or body mass index (source: ClinPGx)
Gene: Protein-coding gene on chromosome 4 (88,725,955 to 89,111,398, reverse strand). Ensembl gene ENSG00000138640.
Subcellular location (Human Protein Atlas): Cytosol; Cell Junctions; Nucleoli
Pathways (Reactome):
Signal Transduction: RAC1 GTPase cycle; RHOA GTPase cycle
Gene Ontology:
Molecular function: GTPase activator activity
Biological process: regulation of small GTPase mediated signal transduction; signal transduction
Cellular component: cytosol
Genetic constraint (gnomAD): Loss-of-function variants: 53 observed, 89.28 expected, observed/expected ratio (o/e) 0.59, 90% interval 0.47 to 0.75. The upper end of that interval is the gene's LOEUF score, 0.75, which puts it in group 3 of 6, group 1 being the genes least tolerant of losing a copy. Missense variants: 881 observed, 1,024.1 expected, observed/expected ratio (o/e) 0.86, 90% interval 0.81 to 0.91. Synonymous variants: 374 observed, 385.53 expected, observed/expected ratio (o/e) 0.97, 90% interval 0.89 to 1.06.
Homologues: Orthologues: chimpanzee FAM13A (99% identical), macaque FAM13A (96% identical), dog FAM13A (87% identical), pig FAM13A (84% identical), rabbit FAM13A (81% identical), tropical clawed frog fam13a (65% identical), guinea pig FAM13A (58% identical), mouse Fam13a (56% identical), rat Fam13a (55% identical), zebrafish fam13a (33% identical), Drosophila melanogaster CG6424 (19% identical). Paralogues in human: FAM13B (38% identical), FAM13C (21% identical).
Diseases named in the same sentence as FAM13A in open-access papers:
FAM13A is named in the same sentence as 41 diseases in open-access papers, as found by Europe PMC text mining. Sharing a sentence is not in itself a finding about the gene and the disease. The quoted sentences say what the papers report.
chronic obstructive pulmonary disease (21 papers, 2015 to 2026). A chronic and progressive lung disorder characterized by the loss of elasticity of the bronchial tree and the air sacs, destruction of the air sacs wall, thickening of the bronchial wall, and mucous accumulation in the bronchial tree. "Single nucelotide polymorphisms (SNPs) at the FAM13A locus are among the most commonly reported risk alleles associated with chronic obstructive pulmonary disease (COPD) and other respiratory diseases; however, the physiological role of FAM13A is unclear." (PMID 38691660, 2024). "In previous studies conducted on human diseases, genome-wide association analysis shows that FAM13A is related to chronic obstructive pulmonary disease (COPD)." (PMID 31795267, 2019). "Recent genome‐wide association studies revealed that the FAM13A gene was associated with human lung function and a variety of lung diseases, including chronic obstructive pulmonary disease, asthma, lung cancer, and pulmonary fibrosis." (PMID 30604588, 2019). "Family with sequence similarity 13 member A (FAM13A) has been previously associated with lung function in several lung diseases, including chronic obstructive pulmonary disease, asthma, lung cancer, and pulmonary fibrosis." (PMID 30604588, 2019). "Genome-wide association studies have identified loci at 15q25 (IREB2) and 4q22 (FAM13A), associated with lung cancer (LC) and chronic obstructive pulmonary disease (COPD)." (PMID 26310313, 2015). "A recent study showed that SNP (rs3017895 located in the FAM13A) may contribute to OC, which had a strong association with chronic obstructive lung disease including emphysema in GWAS." (PMID 38486201, 2024). "FAM13A is also implicated in chronic obstructive pulmonary disease COPD)." (PMID 37019990, 2023). "Recent genome‐wide association studies reveal that the FAM13A gene was associated with a variety of lung diseases, including chronic obstructive pulmonary disease, asthma, lung cancer, and pulmonary fibrosis (Corvol, Hodges, Drumm, & Guillot, 2014; Hawkins & Mora, 2017)." (PMID 30604588, 2019). "Previously, FAM13A gene variants were indicated as risk factors for chronic lung diseases, including chronic obstructive pulmonary disease (COPD), lung cancer, and cystic fibrosis." (PMID 37107672, 2023). "Genetic variants in FAM13A are associated with different types of chronic respiratory diseases, including chronic obstructive pulmonary disease (COPD), cystic fibrosis, and lung cancer." (PMID 37391706, 2023). "A more recent study focused on GWAS variants in or near the FAM13A (family with sequence similarity member 13A) associated with chronic obstructive pulmonary disease (COPD)." (PMID 33691767, 2021). "Previously, FAM13A gene variants were indicated as risk factors of lung cancer, chronic lung diseases including chronic obstructive pulmonary disease (COPD) and cystic fibrosis." (PMID 33919074, 2021). "Family with sequence similarity 13 member A (FAM13A) genetic variants have been associated with several chronic respiratory diseases including chronic obstructive pulmonary disease (COPD), cystic fibrosis, idiopathic pulmonary fibrosis (IPF) and lung cancer." (PMID 31900205, 2020). "Family with sequence similarity 13, member A (FAM13A) is a susceptibility gene in chronic obstructive pulmonary disease (COPD) that has been implicated in COPD progression in genome-wide association studies." (PMID 31164635, 2019). "Initially, FAM13A was genetically associated with the lung function phenotype, with FAM13A genetic variants shown to be associated with lung cancer and several chronic lung diseases including chronic obstructive pulmonary disease (COPD), cystic fibrosis, and idiopathic pulmonary fibrosis (IPF)." (PMID 31900205, 2020).
chronic obstructive pulmonary disease (continued). "Single nucleotide polymorphisms (SNPs) in FAM13A have been widely associated with chronic obstructive pulmonary disease (COPD), asthma severity, lung cancer as well as pulmonary fibrosis, underscoring an important involvement of FAM13A in human lung disease etiology." (PMID 30301961, 2019). "FAM13A, a lung-enriched gene encoding a protein with a characteristic RhoGAP domain, is increasingly recognized for its pleiotropic roles across multiple lung diseases, including chronic obstructive pulmonary disease (COPD), pulmonary fibrosis (PF), asthma, and lung cancer." (PMID 42266412, 2026). "FAM13A is a small GTPase that, when downregulated, was implicated in idiopathic pulmonary fibrosis (IPF) and surprisingly, when overexpressed, was implicated in other respiratory diseases, like chronic obstructive pulmonary disease (COPD) or cancer." (PMID 32365523, 2020).
lung cancer (17 papers, 2011 to 2026). A malignant neoplasm involving the lung. "We confirmed the association between IREB2 gene and lung cancer and between FAM13A gene and COPD in Polish patients." (PMID 26310313, 2015). "In a human lung cancer cell line, FAM13A long and short transcripts were detected, and in lung tissue samples, expression of the short isoform correlated with levels of hypoxia-inducible factor 1α, suggesting a link between FAM13A and hypoxic responses." (PMID 38691660, 2024). "We demonstrated that FAM13A depleted post-hypoxic cells have a decreased metastatic potential, which indicates FAM13A as a potential therapeutic target in lung cancer." (PMID 33919074, 2021). "In our previous report, induction of FAM13A in lung cancer cells was confirmed in both in vitro and ex vivo models in short-term cultures after 72 h of hypoxia." (PMID 33919074, 2021). "Our data demonstrated that FAM13A depleted post-hypoxic cells have a decreased cell proliferation ability and metastatic potential, which indicates FAM13A as a potential therapeutic target in lung cancer." (PMID 33919074, 2021). "To elucidate the influence of FAM13A gene on lung cancer cells migration we applied the wound healing assay." (PMID 33919074, 2021). "In our previous study, we have indicated that the expression of FAM13A was significantly up-regulated under hypoxia conditions in two lung cancer cell lines (A549, CORL-105, p < 0.001) and in lung cancer tissue fragments (p = 0.0004)." (PMID 33919074, 2021). "So far, few data are available on the FAM13A hypoxia-dependent regulation and its contribution to lung cancer progression." (PMID 33919074, 2021). "As such, it will be of interest in a future study to find if the participation of FAM13A in the occurrence of EMT is a common mechanism linked with both COPD and lung cancer." (PMID 34210319, 2021). "Based on these results, we concluded that FAM13A shRNA inhibits invasion of lung cancer in a cell type-specific manner." (PMID 33919074, 2021). "Studies have reported that variants in the family with sequence similarity 13 member A (FAM13A) are associated with chronic lung diseases, including COPD, asthma, lung cancer, and pulmonary fibrosis." (PMID 34210319, 2021). "In our study we generated stable FAM13A knockdown in lung cancer cells, which allowed us to conduct experiments during longer time period." (PMID 33919074, 2021). "We previously showed that FAM13A was significantly up-regulated in lung cancer cell lines (A549, CORL-105) and non-small cell lung cancer fragments cultured ex vivo, after exposure to chronic hypoxia." (PMID 33919074, 2021). "Boyden chamber invasion assay was used to analyze the influence of FAM13A silencing on the invasive properties of the two lung cancer cell lines." (PMID 33919074, 2021). "To examine the impact of FAM13A gene silencing on lung cancer cells proliferation under hypoxia, we performed series of tests, including VPD assay, MTS test and also BrdU assay." (PMID 33919074, 2021). "We therefore performed a two-hybrid screening to identify protein partners of FAM13A using a human lung cancer cDNA library." (PMID 31900205, 2020). "FAM13A was also reported as a hypoxia-induced gene in non–small cell lung cancer, which was overexpressed under hypoxia conditions." (PMID 33194705, 2020). "This study design enabled us to determine the possible link between COPD and lung cancer patients related to IREB2 and FAM13A variants." (PMID 26310313, 2015). "Based on the results of this study, the G0 genes conferring protection from COPD and lung cancer include the rs7671167 SNP (FAM13A gene on the Chr 4q22 locus) and the rs1489759 and rs2202507 SNPs (GYPA and HHIP genes on the Chr 4q31 locus)." (PMID 21304900, 2011). "Using human lung cancer cell lines and Xenopus embryo overexpression studies, Jin and colleagues showed that FAM13A could activate the WNT signaling pathway." (PMID 38691660, 2024).
lung cancer (continued). "It was shown that genetic variants in FAM13A gene may determine susceptibility to COPD and lung cancer by dysregulating the repair processes in airways and leading to emphysema, fibrosis of small bronchi and chronic inflammation." (PMID 35954482, 2022). "FAM13A is the second gene with a strong association with COPD and lung cancer." (PMID 35954482, 2022). "In this study we decided to analyze the impact of FAM13A knockdown in lung cancer cell lines." (PMID 33919074, 2021). "Based on the current results we assume that the hypoxia-induced FAM13A overexpression may diminish the occurrence of EMT in lung cancer cells, but further studies are needed to verify this hypothesis." (PMID 33919074, 2021). "FAM13A has been reported as a downstream effector of EMT inducer TGF-β in A549 lung cancer cells." (PMID 34210319, 2021). "Since FAM13A was also genetically associated with IPF and lung cancer, further studies may help to understand the consequences of these interactions in the development of these diseases." (PMID 31900205, 2020). "In ST2, AS of FAM13A, a key regulator of lung cancer, was discovered as a splicing signature." (PMID 31729991, 2019). "Genome-wide association studies (GWAS) have identified several variants of FAM13A genes that are strongly associated with different types of chronic respiratory diseases, including chronic obstructive lung disease (COPD), pulmonary fibrosis (PF), asthma, and lung cancer." (PMID 37391706, 2023). "None of the FAM13A SNPs showed significant associations with lung cancer cases." (PMID 26310313, 2015). "We can assume that FAM13A gene is a crucial member of hypoxia-response gene set in NSCLC, however our understanding of its contribution in lung cancer progression is still limited." (PMID 33919074, 2021). "Furthermore, the expression of FAM13A is significantly increased in both COPD and lung cancer tissues." (PMID 34210319, 2021). "This is also relevant as the proportion of COPD patients who eventually develop lung cancer may be as high as 25–30% and the frequencies of several disease-related SNPs are very similar between lung cancer and COPD groups (eg FAM13A, HHIP)." (PMID 21304900, 2011). "This might explain why the lung cancer GWA studies to date failed to consistently identify the Chr4q31 (HHIP/GYPA) and Chr4q22 (FAM13A) loci as a protective loci, and the Chr 5q33 (ADAM19) locus as a possible susceptibility locus." (PMID 21304900, 2011).
pulmonary fibrosis (16 papers, 2016 to 2026). Chronic progressive interstitial lung disorder characterized by the replacement of the lung tissue by connective tissue, leading to progressive dyspnea, respiratory failure, or right heart failure. "For example, an 11.32-fold decrease in a peptide from FAM13A (family with sequence similarity 13 member A) was consistent with lung fibrosis-associated FAM13A down regulation." (PMID 34711247, 2021). "A separate candidate was FAM13A, which has previously been associated with other lung conditions, e.g., idiopathic pulmonary fibrosis and COPD." (PMID 27473260, 2016). "For example, M2 macrophage-derived exosomes containing high levels of miR-328 exacerbate pulmonary fibrosis by regulating Family with sequence similarity 13, member A (FAM13A)." (PMID 38655063, 2024). "Decreased FAM13A peptide levels were consistent with a decrease in the protein during lung fibrosis." (PMID 34711247, 2021). "In conclusion, our study demonstrated that miR-328-containing exosomes derived from M2 macrophages stimulate pulmonary fibrosis via silencing FAM13A in a rat model." (PMID 31164635, 2019). "Intriguingly, SNPs for DSP and FAM13A are associated with both COPD and pulmonary fibrosis but with opposite risk alleles, suggesting a potential mechanistic link between the two diseases and inviting further study to understand the contribution of these genes in particular." (PMID 35857525, 2022). "Studies on FAM13A regulatory mechanisms have moved from human COPD, fibrosis of the lung, and NSCLC, to insulin sensitivity, adipocyte differentiation, and proliferation, and the correlation between the hypoxic state and other aspects." (PMID 34672860, 2021).
lung diseases (15 papers, 2015 to 2026). "Interestingly, some studies show that specific FAM13A loci may be associated not only with pulmonary disorders, but also with metabolic complications." (PMID 37107672, 2023). "FAM13A, ERBB2, and TCF7 are associated with lung function and various pulmonary diseases in mammals." (PMID 41190333, 2025). "Outside the context of lung diseases, at the cellular level, FAM13A is able to control the cell shape." (PMID 31900205, 2020). "Among the genes identified on the T. compressicauda, the gene fam13a is involved in signal transduction (GO:0007165) and has been related to different lung diseases with its activity induced by low levels of O2." (PMID 31072350, 2019). "This approach provided an assessment of the potential role of IREB2 and FAM13A genes in lung disease development in the Polish population." (PMID 26310313, 2015). "For the FAM13A (family with sequence similarity member 13A) gene located in the second important region on OAR6, a detailed GWAS study found an association with lung disease in humans, whereas other studies in sheep confirmed an association with milk yield and body/bone weight in cattle." (PMID 37932811, 2023). "Finally, SNVs in the FAM13A gene have been associated with an increased risk of COPD and IPF; the most critical part of the FAM13A protein is its N-terminal extension containing the Rho-GAP domain involved in lung endothelial barrier function, which is often deregulated in lung diseases." (PMID 40076669, 2025). "While intensive genomic studies have been performed to reveal its involvement in lung diseases, the biological role of FAM13A protein is still not completely elucidated." (PMID 31900205, 2020).
cystic fibrosis (9 papers, 2019 to 2025). Autosomal recessive disorder caused by pathogenic variants in the CFTR gene (cystic fibrosis transmembrane conductance regulator), which encodes a chloride and bicarbonate channel expressed in epithelial cells, and follow the diagnosis criteria. "In a cystic fibrosis study, the FAM13A long isoform was detected in undifferentiated primary human basal airway epithelial cells, and FAM13A siRNA knockdown modulated RhoA activity, actin stress fiber formation, and EMT." (PMID 38691660, 2024). "FAM13A is a modifier gene that regulates RhoA activity, actin cytoskeleton dynamics, and epithelial-mesenchymal transition in the cystic fibrosis lung phenotype." (PMID 39143382, 2024). "In their studies, FAM13A was demonstrated to increase the susceptibility to airway obstruction independent of smoking status and to closely relate to the EMT of cystic fibrosis airway." (PMID 34210319, 2021). "It was reported that the reduced expression of FAM13A resulted in increased RhoA activation in A549 cells and primary human bronchial epithelial cells from cystic fibrosis patients." (PMID 33919074, 2021). "FAM13A is a modifier gene of cystic fibrosis lung phenotype regulating rhoa activity, actin cytoskeleton dynamics, and epithelial–mesenchymal transition." (PMID 30604588, 2019).
emphysema (9 papers, 2014 to 2024). "However, the observed differences, such as the FEV1-emphysema relationship in alternate FAM13A genotypes, could provide clues regarding the underlying mechanisms by which these GWAS regions influence disease susceptibility." (PMID 24964944, 2014). "One study reported the FAM13A interacts with PP2A and β‐catenin to regulate β‐catenin protein stability it could promote cell proliferation, at the same time, the result also showed FAM13A determines susceptibility to emphysema by regulating β‐catenin signaling." (PMID 30604588, 2019). "In previous GWA studies, in mainly smokers, on classical COPD phenotypes like emphysema and chronic bronchitis, the well-known general COPD genes (HHIP, CHRNA and FAM13A) were consistently identified." (PMID 30845926, 2019). "We implicated genes that are genetically regulated in known COPD-susceptibility loci, such as FAM13A, and also found genes in regions that were not previously reported: WNT3 for severe COPD, and DCBLD1 and LILRA3 for quantitative emphysema." (PMID 29566699, 2018).
asthma (8 papers, 2016 to 2026). "The gene encoding the family with sequence similarity 13 member A (FAM13A) has also been associated with asthma." (PMID 31637021, 2019). "In particular, two of the PM10-related CpGs mapped to FAM13A (cg00905156) and NOTCH4 (cg06849931) genes associated with lung function and asthma, and both CpGs were significant (p < 0.05) in 7- to 9-year-olds, although only the direction of the association of the CpG in FAM13A was consistent." (PMID 31470889, 2019). "Interestingly, FAM13A regulates β-catenin stability and augments Wnt signaling in asthma." (PMID 31637021, 2019). "Finally, FAM13A (a gene associated with COPD) has been shown to predict lung function abnormalities in non-Hispanic white and African American subjects with asthma, together with other lung function genes." (PMID 26986948, 2016).